IL17A (interleukin 17A)
Diseases named in the same sentence as IL17A in open-access papers (continued):
Sharing a sentence is not in itself a finding about the gene and the disease.
Chagas disease (80 papers, 2010 to 2026). A parasitic infection caused by Trypanosoma cruzi. "In the present study, we analysed three IL17A genetic variants (rs4711998, rs8193036 and rs2275913) regarding the predisposition to Trypanosoma cruzi infection and the development of chronic Chagas cardiomyopathy (CCC) in different Latin American populations." (PMID 32193469, 2020). "In conclusion, in this work, we found an association of IL17A rs2275913 with Chagas disease in a large cohort composed of different Latin American countries, validating previous findings." (PMID 32193469, 2020). "Finally, further studies on this gene accounting for functional analyses and heterogeneity among populations, would be necessary for the complete understanding of IL17A polymorphisms in Chagas disease." (PMID 32193469, 2020). "A follow-up study in school-aged children with Chagas disease found that higher IL-17A levels were associated with the persistence of infection after treatment with benznidazole, suggesting this cytokine could be a possible biomarker for nonresponse to treatment and the persistence of infection." (PMID 33506056, 2021). "In addition, high IL17A levels were also associated with better heart function in Chagas disease." (PMID 33193300, 2020). "Salmonella triggers IL-35 and IL-10 production by B cells, and we demonstrated previously that Trypanosoma cruzi infection leads B cells to produce IL-17A." (PMID 32398312, 2020). "Additional studies are necessary, however, to establish the effect of the AA genotype on IL17A serum levels in Chagas disease patients." (PMID 33193300, 2020). "IL-6 improves the cytotoxic CD8+ T cell dysfunction triggered by nitric oxide in patients with Chagas disease; additionally, we recently demonstrated that IL-17RA and IL-17A are critical factors for sustaining CD8+ T cell immunity to T. cruzi." (PMID 32398312, 2020). "Protective immunity against Trypanosoma cruzi, the causative agent of Chagas disease, depends on the activation of macrophages by IFN-γ and IL-17A." (PMID 27650379, 2016). "Our data support a protective role of IL17A AA, IL18 AA, and IL1B TC genotypes against development/progression of cardiomyopathy and a modulatory effect of the IL6 CG genotype on the risk of parasitemia in Chagas disease." (PMID 33193300, 2020). "Interleukin 17A (IL-17A) has been associated with protective rather than pathogenic response in Chagas disease (ChD)." (PMID 28278264, 2017). "The aim of this study was to investigate possible associations between genetic polymorphisms of IL17A G197A (rs2275913) and IL17F T7488C (rs763780) with Chagas Disease (CD) and/or the severity of left ventricular systolic dysfunction (LVSD) in patients with chronic Chagas cardiomyopathy (CCC)." (PMID 28470012, 2017). "In order to evaluate the possible association of IL17A G197A and IL17F T7488C SNPs and Chagas disease, the allele and genotype frequencies between patients (CD) and their subgroups (CCC, without CCC, with LVSD, without LVSD, Mild/moderate LVSD, severe LVSD) and controls were compared." (PMID 28470012, 2017). "Recently, it was discovered that through the secretion of IL-17A, Th17 cells trigger the macrophage function of NADPH oxidase as well as CD8 T-cells to provide direct protection in Chagas disease." (PMID 31553732, 2019). "The absence of IL-17RA and IL-17A/F during Trypanosoma cruzi infection resulted in increased tissue parasitism and reduced frequency of parasite-specific CD8+ T cells." (PMID 30364284, 2018). "In our cohort of chronically infected Chagas disease patients, those with detectable T. cruzi parasitemia measured through RT-PCR in peripheral blood had a higher concentration of pro-inflammatory cytokines (TNF-α, IL-1β, IL-6 and IL-17A) and IL-4 than those with negative RT-PCR." (PMID 38133693, 2023).
chronic mucocutaneous candidiasis (79 papers, 2010 to 2026). "Auto-Abs against IL-17A and IL-17F underlie chronic mucocutaneous candidiasis and mimic inborn errors of IL-17A/F." (PMID 37307437, 2023). "Chronic mucocutaneous candidiasis (CMC) is associated with anti-interleukin (IL)-17A, anti-IL-17F, or anti-IL-22 autoantibodies." (PMID 31892200, 2019). "Patients with the STAT1 mutation also have hindered the production of IL-17A, IL-17F, and IL-22 by T cells, and, therefore, these patients have impaired IL-17 immunity and are predisposed to chronic mucocutaneous candidiasis." (PMID 28300772, 2017). "Chronic mucocutaneous candidiasis (CMC) has been observed in individuals with anti-IL-17A, anti-IL-17F, and anti-IL-22 autoantibodies, resulting from these autoantibodies blocking the Th-17 immunity." (PMID 35003106, 2021). "Chronic mucocutaneous candidiasis (CMC) is a recurrent infection of skin, mucosae and nails (onychomycosis), frequently seen in individuals with mutations that affect Th17 cells, the cytokines IL-17A and IL-17F, or their receptor IL-17RA." (PMID 25849644, 2015). "In particular, patients with disseminated Talaromyces marneffei infection or histoplasmosis should be screened for AIGAs, patients with Cryptococcus gattii infection for anti-GM-CSF antibodies, and patients with chronic mucocutaneous candidiasis for anti-IL-17A/F (IL-22), where possible." (PMID 37623553, 2023). "Patients with autosomal recessive (AR) IL-12p40 or IL-12Rβ1 deficiency display Mendelian susceptibility to mycobacterial disease (MSMD) due to impaired IFN-γ production and, less commonly, chronic mucocutaneous candidiasis (CMC) due to impaired IL-17A/F production." (PMID 36763636, 2023). "Interestingly, neutralizing autoantibodies against Th17 cell cytokines IL-17A, IL-17F, and IL-22 have been reported in chronic mucocutaneous candidiasis (CMC) patients with autoimmune polyendocrinopathy syndrome-1 (APS-1) or thymoma." (PMID 21079687, 2010). "Inborn errors of the IL-17A/F-responsive pathway lead to chronic mucocutaneous candidiasis (CMC) as a predominant clinical phenotype, without other significant clinical manifestations apart from mucocutaneous staphylococcal diseases." (PMID 37577484, 2023).
candidiasis (77 papers, 2011 to 2026). Infection with the organism Candida. "In a recent study, IL-17A has been shown to confer protection against invasive candidiasis, and IL-17 deficiency has been shown to enhance susceptibility to C. albicans infections at mucosal sites." (PMID 34696267, 2021). "Our data revealed that intestinal microbiota plays a protective role in invasive candidiasis by enhancing IL-17A production in our model system." (PMID 32460890, 2020). "While IL-17A administration protects antibiotic-exposed mice from invasive candidiasis." (PMID 40953078, 2025). "Therefore, intestinal microbiota plays a protective role in invasive candidiasis via regulating IL-17A production." (PMID 32460890, 2020). "Treatment with recombinant IL-17A could improve the survival of ABX mice during invasive candidiasis." (PMID 32460890, 2020). "Restoring the intestinal microbiota by FMT could enhance the defense ability and the expression of IL-17A in ABX mice against invasive candidiasis." (PMID 32460890, 2020). "In addition, the level of IL-17A in ABX mice was significantly lower than that in the CNV group during invasive candidiasis." (PMID 32460890, 2020). "IL-17A treatment could improve survival of ABX mice after invasive candidiasis." (PMID 32460890, 2020). "Furthermore, FMT could increase the serum level of IFN-γ and IL-17A in ABX mice during invasive candidiasis." (PMID 32460890, 2020). "Of the cytokines induced, IL-1α, IL-1β, IL-6, IL-10, IL-17A, IL-18, IFN-γ, and TNF-α have been previously shown to play an important role in the pathogenesis of invasive candidiasis in vivo." (PMID 22916017, 2012).
liver disease (77 papers, 2010 to 2026). "IL-17A is a newly-discovered factor secreted by T-helper 17 lymphocytes, associated with the occurrence and development of various liver diseases." (PMID 35295601, 2022). "IL-17A are key biological indicators of immunopathogenesis in chronic hepatitis, and Th17-associated cytokines are linked to liver disease progression in HCV disease." (PMID 36405584, 2022). "Was the down-regulation of serum IL-17 a cause of the therapeutic effect of BMSCs on patients/mice with liver diseases, or was merely a satellite phenomenon?" (PMID 24314294, 2013). "Previous studies have confirmed that interleukin-17A (IL-17A) promoted fibrosis in some liver diseases." (PMID 42085509, 2026). "This work highlights the importance of host-mycobiome interactions in shaping inflammatory liver disease and supports further investigation into targeted strategies aimed at modulating IL-17A-mediated immune responses in patients with MASLD." (PMID 41716747, 2025). "A study investigating the mechanistic differences between IL-17A and IL-17F in the context of liver disease, using transcriptional network analysis, revealed distinct pathway activation profiles between the two cytokines." (PMID 41200179, 2025). "IL-17F expression declines progressively with increasing severity of liver disease, independently of IL-17A." (PMID 41200179, 2025). "We will focus on the type 3 cytokines IL-17A and IL-22, their roles during the different stages of liver disease in general and MASLD in particular and their therapeutic potential." (PMID 39156888, 2024). "HBV-induced liver disorders are exacerbated by interleukin (IL)-17 A. It has only been recently discovered that IL-17 and its byproducts play crucial roles in the development of chronic HBV-related liver disorders." (PMID 37946175, 2023). "Comorbidity data, including Charlson scores, were comparable across IL-17A tertiles with the exception of liver disease, which was more prevalent in patients in the highest IL-17A tertile versus lower tertiles." (PMID 35422004, 2022). "We aim to update what is known about IL-17A, IL-22, and retinoic acid in the pathobiology of liver diseases." (PMID 34211477, 2021). "IL-17A, a promising therapeutic target in liver diseases, was inhibited by reversine at a low dose but was not affected by this drug at a high dose." (PMID 33817258, 2020). "The activity of IL-17A and Th17 cells in liver disease has been investigated extensively both in experimental liver injury models and human liver diseases." (PMID 24069246, 2013). "However, the role of other cytokines (IL-10, IL-17A, IL-1RA, IL-8) regarding the prognosis of patients with severe portal hypertension receiving TIPS remains poorly investigated." (PMID 35295601, 2022). "However, an increase in IL-17A expression has been shown in the advanced stages of HBV-related liver disease by the immunohistochemistry on fresh biopsies of HBV+ patients or patients with non-alcoholic steatohepatitis." (PMID 34211477, 2021). "Notably, IL-17A levels correlate with a variety of human hepatic disorders, including alcoholic liver disease, primary biliary cirrhosis, chronic hepatitis B and C, liver transplant rejection and hepatocellular carcinoma." (PMID 26895034, 2016). "In summary, IL-17A and IL-22 are particularly significant among type 3 cytokines due to the wide investigation of their roles in the initiation, progression, and resolution of liver disease, notably MASLD, and their therapeutic potential and will thus be the focus of this review." (PMID 39156888, 2024). "The significance of circulating IL-17A has not been completely elucidated, particularly in the case of patients with hepatic diseases." (PMID 33723292, 2021). "Moreover, we demonstrated that IL-33 has an inhibitory effect on IL-25-mediated IL-17A expression in hepatic ILC2, indicating that in IL-33-triggered liver diseases, the development of inflammatory ILC2 might be suppressed." (PMID 31974518, 2020).
liver disease (continued). "IL-17A to date has not been shown to have a major influence on outcome in liver disease models." (PMID 23181064, 2012).
myocarditis (77 papers, 2010 to 2026). Myocarditis is a condition that is characterized by inflammation of the heart muscle (myocardium). "In particular, IFN-γ signaling is needed for spontaneous myocarditis development, while IL-17A, also in this model, has been linked to disease severity and DCM development." (PMID 39768171, 2024). "Th17 cells and their associated cytokines (i.e., IL-17A, IL-6, IL-23) were found to directly correlate with heart failure in a study of patients with clinically suspected myocarditis/acute DCM." (PMID 36937911, 2023). "Sikder with co-workers found that β-hemolytic group C streptococci and group G streptococci caused IL-17A/interferon γ-induced myocarditis and valvulitis." (PMID 36601077, 2022). "IL-1β, IL-6, and IL-17A responses are elevated in men with myocarditis/cardiomyopathy, and associated with poor recovery from heart failure." (PMID 34445539, 2021). "Similarly, P. gingivalis infusion in mice caused myocardial infarction or myocarditis, with inflammation dependent on IL-17A, suggesting Th17 pathways play a role in P. gingivalis-induced cardiovascular inflammation." (PMID 40136726, 2025). "IL-17A, produced by infiltrating Th17 cells, induces the production of monocyte-chemoattracting chemokines by cardiac fibroblasts to recruit inflammatory monocytes, underlining the fine immune cell cross-talk taking place in myocarditis evolution." (PMID 39768171, 2024). "Furthermore, a 2.48-fold overexpression of IL-17A was associated with myocarditis in these patients." (PMID 38202158, 2023). "Furthermore, myocardial fibrosis was reduced in IL-17A–deficient mice, and administering anti-IL-17A mAb to mice with established myocarditis reduced cardiac fibrosis and preserved ventricular function." (PMID 32269577, 2020). "Although IL-17A alone reproduces key aspects of autoimmune-driven fibrosis, future organoid models will incorporate a multifactorial cytokine environment (e.g., TNF-α + TGF-β + IL-17A) to better mimic viral or mixed etiology myocarditis." (PMID 41356193, 2026). "Clearly, from our previous studies, Th17 responses promote heart failure in human myocarditis with IL17A presenting as one of the two elevated biomarker cytokines in non-recovery of normal ejection fraction." (PMID 40181955, 2025). "On the other hand, in this study, it was found that IL-17A is required for the progression of acute myocarditis in dilated cardiomyopathy, and contributes to the development of foci of fibrosis in the myocardium and loss of cardiac function." (PMID 36674665, 2023). "Further, the Lewis rat model of RHD immunized with recombinant M5 protein developed myocarditis and valvulitis characterized by secretion of high levels of IL-17A and IFN-γ suggesting that the two cytokines are together important in the pathology of RHD." (PMID 36815140, 2022). "Th17 cells and related cytokines like IL-17A, IL-17F, IL-22, TNF-α are the major regulators of the late or chronic phase of myocarditis, and IL-17A and IL-17F are signature cytokines." (PMID 32269577, 2020). "They further demonstrated that blockade of IL-17A protected against CVB3-induced myocarditis by increasing COX-2/PGE2 production in the heart." (PMID 27724948, 2016). "On day 7, the mRNA levels of TNF-α, IL-1β and IL-17A were reduced in the group of 0.1 mg/kg nicotine compared to the myocarditis group." (PMID 26507386, 2015). "On day 7, the cardiac IL-1β, TNF-α, IL-6 and IL-17A levels were significantly downregulated in the group of 0.2 and 0.4 mg/kg nicotine compared to the myocarditis group." (PMID 26507386, 2015). "The enhanced expression of IL-17A has been reported in several cardiovascular diseases, including atherosclerosis, myocarditis, dilated cardiomyopathy and myocardial ischemia/reperfusion injury." (PMID 25955429, 2015). "Treatment of T. cruzi infected mice with anti-IL-17A mAb lead to increased myocarditis, premature mortality, and decreased parasite load in the heart, suggesting that IL-17 controls the host resistance." (PMID 22545173, 2012).
myocarditis (continued). "In our previous longitudinal study, elevated IL17A production associated with non-recovery of normal EF in myocarditis patients who did not recover normal EF." (PMID 40181955, 2025). "Studies demonstrated that interleukin-17A (IL-17A), a key inflammatory factor in myocarditis pathogenesis, directly induces ADAMTS1 expression in cultured cardiac fibroblasts, simultaneously promoting myocardial fibroblast proliferation and upregulating synthesis of type I and III collagen." (PMID 41440846, 2025). "IL-17A-related myocarditis can occur in up to 5% of patients with PS." (PMID 37373705, 2023). "IL-17A also contributed to the mechanisms of cardiac injury in the heart transplantation model, angiotensin II-induced hypertensive heart injury, and myocarditis-induced cardiac fibrosis." (PMID 33981320, 2021). "Thus, IL-17A plays a critical role during cardiac remodeling, and is essential for the progression from myocarditis to DCM." (PMID 32269577, 2020). "Because CD4+ T cells were increased by BPA exposure in drinking water, we examined whether IFNγ, IL-4, and/or IL-17A cytokine levels were altered in the heart during acute CVB3 myocarditis following BPA exposure." (PMID 31551929, 2019). "IL-6 might facilitate myocardial fibrosis by regulating downstream IL-17A, promoting the progression of myocarditis into DCM." (PMID 23977238, 2013). "Several cytokines such as IFN-γ, IL-17A, IL-17F promote early tissue damage and progression of DCM of myocarditis." (PMID 38741130, 2024). "In a previous study, in the experimental coxsackievirus-B3-induced myocarditis model, VPA treatment downregulated the expression of IL-17A and upregulated IL-10 cytokine of infected mice through the induction of Treg cell differentiation." (PMID 34067829, 2021). "In a transgenic mouse model expressing a MyHCα-specific T cell receptor on CD4+ T cells, myocarditis developed spontaneously, and the cooperation of IFN-γ and IL-17A was found to be essential for the transition from myocarditis to DCM." (PMID 33466825, 2021). "Our previous studies have supported a Th17 autoimmune pathogenesis where IL17A and IL-6 are elevated in myocarditis patients who do not recover normal EF." (PMID 40181955, 2025). "Mice treated with IL-17A knockout or IL-17A monoclonal antibody exhibited significantly reduced cardiac remodeling and myocardial fibrosis post-myocarditis, and absence of DCM." (PMID 39502194, 2024). "In the case of viral myocarditis, it has been shown that the role of IL-17A as a pro-inflammatory Th17 mediator is not key in the development of acute inflammatory stages of myocarditis, at least in mice." (PMID 36674665, 2023). "Overexpression of IL-17A was ascertained by both immunohistochemistry and western blot analysis, which showed a 2.5-fold increase in the value obtained in no-psoriatic myocarditis and a six-fold increase in the normal myocardial controls." (PMID 37373705, 2023). "In this study we found that exposure to BPA in drinking water elevated proinflammatory cytokines/ receptors in the heart of female mice during CVB3 myocarditis that would typically be elevated in male mice or men with mycarditis such as TLR4, caspase-1, IL-1β, IL-17A, and IFNγ." (PMID 31551929, 2019). "Semiquantitative evaluation of immunostaining (grades from 0 to 4) for IL-17A and TLR4 showed an increased cardiomyocyte expression of IL-17A in PS myocarditis compared with no-psoriatic patients and vs. controls (respectively, 3.95 ± 0.13 vs. 1.91 ± 0.5 and 3.95 ± 0.13 vs. 0.19 ± 0.2)." (PMID 37373705, 2023). "In a TCR transgenic mouse model with spontaneous autoimmune myocarditis progressing into DCM, blocking IFN-γ signaling significantly attenuated myocarditis without affecting the development of DCM, while lack of IL-17A inhibited DCM but had a mild effect on myocarditis." (PMID 32269577, 2020).